RUNX1 (RUNX family transcription factor 1)
Diseases named in the same sentence as RUNX1 in open-access papers (continued):
Sharing a sentence is not in itself a finding about the gene and the disease.
clear cell renal cell carcinoma (7 papers, 2015 to 2025). "The methylation level of the RUNX1 promoter is low in renal clear cell carcinoma, and the expression of RUNX1 is upregulated in renal clear cell carcinoma tissues compared with normal tissues." (PMID 38430423, 2024). "A public dataset from The Cancer Genome Atlas (TCGA) was used to evaluate the role of RUNX1 in clear cell renal cell carcinoma (ccRCC)." (PMID 31592165, 2019). "Our TF family member analysis showed that RUNX1, RUNX2, and RUNX3 were all within the top 5 % of TFs correlated with hypomethylation of RUNX-containing enhancer probes in clear cell renal carcinoma (KIRC) a, b." (PMID 25994056, 2015).
esophageal cancer (7 papers, 2016 to 2025). A primary or metastatic malignant neoplasm involving the esophagus. "Notably, RUNX1 (21q22.12) amplification is linked with increased invasiveness and metastatic potential in esophageal cancer, consistent with patterns of chromosomal instability (CIN)." (PMID 40963872, 2025).
kidney cancer (7 papers, 2015 to 2024). Primary or metastatic malignant neoplasm involving the kidney. "We also identified novel networks with prognostic associations, including RUNX1 in kidney cancer." (PMID 25994056, 2015). "Some of the TENET-identified TFs in KIRC (TFEC, RUNX1, ZNF395) have been previously linked to kidney cancer." (PMID 27833659, 2016). "Furthermore, the relationship between expressions of RUNX1, RUNX2and RUNX3 and prognosis of KIRC were performed by GEPIA and the results revealed that higher expression of RUNX1 had poorer overall survive (OS) in kidney cancer patients (p < 0.001)." (PMID 34294773, 2021). "Other TF networks we identified, such as RUNX1/2 and its association with poor outcome in kidney cancer, have never been reported and will form the basis for future studies." (PMID 25994056, 2015). "Overall, the obtainedresults indicated significantly elevated expression of RUNX1 (with fold changes of 6.58 to 6.51) and RUNX3 (with fold changes of 2.7 to 8.32) in kidney cancer." (PMID 34294773, 2021). "RUNX1 and RUNX2 genes might be also involved in kidney cancer." (PMID 34973136, 2023).
leukocytosis (7 papers, 2015 to 2024). "In another distinct BMT mouse model, Evi-1 seemed to collaborate with an RUNX1 mutant harboring a point mutation in the Runt homology domain (D171N) to induce with an identical phenotype characterized by marked hepatosplenomegaly, myeloid dysplasia, leukocytosis, and biphenotypic surface markers." (PMID 26674644, 2015). "Statistical analysis indicated a significant positive correlation between RUNX1 mRNA level and leukocytosis (p = 0.035, r = 0.27), higher expression levels were found in patients with greater leukocytosis." (PMID 36005134, 2022). "A higher RUNX1 transcript level correlates with greater leukocytosis while RUNX3 expression is reduced in Philadelphia chromosome bearers." (PMID 36005134, 2022). "At 9 months post-BMT, mice harboring combined RUNX1 and ASXL1 mutations developed disease characterized by marked splenomegaly, hepatomegaly, and leukocytosis with a shorter latency." (PMID 31640815, 2019). "Moreover, it was found that high levels of RUNX1 gene expression correlate with higher leukocytosis in the investigated ALL cohort (p = 0.035)." (PMID 36005134, 2022). "There was marked leukocytosis in all the patients, with a mean value of 71.43 ± 37.93, a range of 35-150 × 109/L, and a p-value of 0.0002 suggestive of marked leukocytosis in positive AML-M2 with RUNX1/RUNX1T1 patients." (PMID 39735012, 2024).
liver cancer (7 papers, 2020 to 2023). An epithelial or non-epithelial malignant neoplasm that arises from the liver. "Given that RUNX1 causes hematological malignancies mainly through somatic mutations and functions as a tumor suppressor, RUNX1 is more promising as a target for the treatment of solid tumors, where it is a tumor-promoting gene, with the exception of breast and liver cancers." (PMID 36429115, 2022). "By transfecting RUNX1-expressing vectors into liver cancer cells, Liu and colleagues found that RUNX1 negatively influenced tumour cell potential of metastasis and proliferation." (PMID 37759525, 2023). "For example, investigating liver targeting through liposomes or bile acids in liver cancer could be possible future strategies to evaluate the role of RUNX1 in the pathogenesis of NAFLD." (PMID 35740337, 2022). "In liver cancer, our results showed that RUNX1 but not RUNX2 or RUNX3 was upregulated in tumor tissue in comparison with normal tissue." (PMID 32746865, 2020).
lymphoid neoplasm (7 papers, 2011 to 2025). A neoplasm composed of a lymphocytic cell population which is usually malignant (clonal) by molecular genetic and/or immunophenotypic analysis. "Finally, the possible contribution of germline mutations, including DDX41, RUNX1, ETV6, ANKRD26, and POT1, which have been associated with the occurrence of both myeloid and lymphoid neoplasms, is an intriguing point to be explored in future studies." (PMID 34733777, 2021).
non-small cell lung carcinoma (7 papers, 2016 to 2024). A group of at least three distinct histological types of lung cancer, including non-small cell squamous cell carcinoma, adenocarcinoma, and large cell carcinoma. "Furthermore, RUNX1 displayed increased activities and serves as a key driver of fibroblast states, linking to the promotion of macrophage-myofibroblast transition in non-small-cell lung carcinoma." (PMID 39505867, 2024). "In addition, RUNX1 is overexpressed in non-small cell lung cancer (NSCLC) and promotes the invasion of NSCLC cells." (PMID 31592165, 2019).
osteoporosis (7 papers, 2020 to 2024). A condition of reduced bone mass, with decreased cortical thickness and a decrease in the number and size of the trabeculae of cancellous bone (but normal chemical composition), resulting in increased fracture incidence. "Here we describe osteoporosis with impaired bone microarchitecture in a young man with a novel and potentially pathogenic germline genetic variant in runt‐related transcription factor 1 (RUNX1)." (PMID 37701147, 2023). "Interestingly, in an ovariectomized animal model used to simulate estrogen depletion‐induced osteoporosis, RUNX1 overexpression via an adeno‐associated virus (AAV)‐mediated gene expression significantly increased bone volume." (PMID 37701147, 2023). "Our Runx1 conditional deletion mouse models revealed that Runx1 is critical for osteoblast lineage commitment and maintenance and Runx1 deficiency can be an important genetic cause leading to osteoporosis." (PMID 33476325, 2021). "Runx1 overexpression can rescue bone loss in OVX-induced osteoporosis." (PMID 33476325, 2021). "Notably, Runx1 overexpression rescued bone loss in OVX-induced osteoporosis." (PMID 33476325, 2021). "The results of another experiment showed that RUNX1 deleted mice with normal bone formation had a significant osteoporosis phenotype at both the immature and adult phases." (PMID 36541023, 2023). "According to the research of osteoporosis in male including 822 volunteers aged 65 years or older, results pointed out that RUNX1 was a potential genetic regulatory of bone formation by measuring cortical bone and cancellous density in humans." (PMID 36541023, 2023). "Collectively, Runx1 maintains adult bone homeostasis from bone loss though up-regulating Bmp7/Alk3/Smad1/5/8/Runx2/ATF4 and WNT/β-Catenin signaling pathways, and targeting Runx1 potentially leads to novel therapeutics for osteoporosis." (PMID 33476325, 2021). "In conclusion, our research indicates that hsa_circ_0026827 promotes osteoblast differentiation of DPSCs via Beclin1 and the RUNX1 signaling pathways by sponging miR-188-3p, which suggests novel therapeutics for osteoporosis treatment." (PMID 32671065, 2020). "By analogy with the preclinical studies of RUNX1 overexpression, there may also be a role for RUNX1 as a potential therapeutic target for novel osteoporosis therapy." (PMID 37701147, 2023). "However, in this study, our results demonstrated that Runx1 conditional knockout mice using Twist2-Cre and Col1α1-Cre (Runx1 CKO) displayed a severe osteoporosis phenotype." (PMID 33476325, 2021). "Runx1 may be a potential target of clinical significance in the development of novel treatment strategies for osteoporosis and other degenerative bone diseases." (PMID 33476325, 2021). "Taken together, these results suggest that Runx1 might be a potent therapeutic target in OA and osteoporosis." (PMID 34876557, 2021). "Radiographic and uCT analyses demonstrated that AAV-mediated overexpression of Runx1 with or without its binding partner, Cbfβ, significantly increased bone volume after estrogen depletion induced osteoporosis." (PMID 33476325, 2021). "However, both Twist2-Cre and Col1α1-Cre Runx1 mutant CKO mice displayed a severe osteoporosis phenotype, while a more severe osteoporosis phenotype was observed in 8-month-old mutant mice." (PMID 33476325, 2021). "Runx1 maintained adult bone homeostasis and bone differentiation though upregulating Bmp7/Alk3/Smad1/5/8/Runx2/ATF4 and WNT/β-Catenin signaling pathways, suggesting that targeting Runx1 might be a novel therapeutics for osteoporosis." (PMID 37156809, 2023).
renal carcinoma (7 papers, 2020 to 2024). A carcinoma arising from the epithelium of the renal parenchyma or the renal pelvis. "BCL3 and EP300 as prognostic factors for KIRC, and upregulated RUNX1 is closely associated with renal cancer progression." (PMID 38292868, 2024). "Additionally, overexpression of RUNX1 resulted in significantly poorer clinical survival in patients with renal cancer." (PMID 35534796, 2022).
sarcopenia (7 papers, 2016 to 2025). Progressive decline in muscle mass due to aging which results in decreased functional capacity of muscles. "RWE suppressed age-related increases in expression of Gadd45α and Runx1 in old male and female quadriceps muscles, respectively, and this was associated with amelioration of sarcopenia." (PMID 27964759, 2016). "In aging mouse models, RUNX1 upregulation correlates with NMJ instability preceding sarcopenia and regulates denervation-related genes, including acetylcholine receptor subunits and atrophy markers such as MuRF1 and Atrogin-1." (PMID 40917776, 2025). "Other studies have found similar results in aged mice, showing Gadd45a and Runx1 are elevated with a KD, which has been shown to mitigate sarcopenia." (PMID 36458175, 2022). "The expression of Runx1 increased substantially from 15 to 24 month in quadriceps muscles of female mice, month age coincided with the transition to sarcopenia." (PMID 35812340, 2022). "RUNX1 expression is increased in aged muscle alongside denervation and sarcopenia and can similarly be reduced by physical intervention." (PMID 32154891, 2020). "In a small number of older obese men and women and in aged female mice with sarcopenia resistance training, which is known to preserve the neuromuscular junction and improve innervation, was found to reduce RUNX1 expression." (PMID 32154891, 2020). "However, chronic denervation, aging, or sustained stress leads to persistent RUNX1 upregulation, which correlates with progressive NMJ dysfunction and sarcopenia." (PMID 40917776, 2025).
skin cancer (7 papers, 2016 to 2022). "RUNX1 maintains the active/phosphorylated form of the oncogene STAT3 by inhibiting SOCS3/4 in skin cancer, thereby increasing cell survival, proliferation, and invasion." (PMID 36551618, 2022). "These functions of Runx1 have been shown in breast, prostate, lung, and skin cancers, presenting a relationship between different subtypes of cancers and stages of tumor progress." (PMID 32952599, 2020). "In mouse skin cancer formation and maintenance, signal transducer and activator of transcription 3 (Stat3) is activated by Runx1 signaling as a tumor promoter." (PMID 30046048, 2018). "Runx1 acts is a tumor promoter in mouse skin cancer formation and maintenance by promoting Stat3 activation and Tgfb3 expression is often upregulated in cancer formation." (PMID 30046048, 2018). "In addition, Runx1 is also important for skin stem cells as well as skin cancer development." (PMID 30026553, 2018). "Furthermore, Runx1 maintained Stat3 activity in the epidermis and in skin cancer cells." (PMID 30046048, 2018). "The hypothesis that RUNX1 could affect different steps in tumor promotion has also been described in skin cancer where it was found that RUNX1 is important for both, tumor initiation and progression, while it had been previously shown that RUNX1 was not essential for adult tissue maintenance." (PMID 26735887, 2016).
viral infection (7 papers, 2020 to 2025). "In contrast, transient pharmacological DNA methyltransferase inhibition during priming impairs repression of Tfh-associated genes while properly silencing Runx1, and results in enhanced Tfh cell functionality in primary and secondary responses to viral infections." (PMID 39677644, 2025). "Here, we found that Runx1 overexpression represses GC Tfh differentiation during viral infection, which is likely via repression of ICOS expression in early Tfh and Th1 cells." (PMID 39677644, 2025). "Together, these results unveiled a role of RUNX1 located at the NLRP12 promoter that is required to suppress the transcriptional activation of NLRP12 under IFN-I stimulation or during virus infection." (PMID 36719379, 2023). "It is also demonstrated that RUNX1 negatively regulates innate immune responses during viral infection." (PMID 35248104, 2022). "Because the N-terminus of RUNX1 was shown to interact with adenoviral proteins and affect their localization, we reasoned that the fusion products may have different effects on the virus infection." (PMID 41497616, 2025). "We show that virus infection, nucleic acid, and IFN-α treatment markedly reduced NLRP12 expression by RUNX1-dependent epigenetic regulation, as observed in SLE patient–derived PBMCs." (PMID 36719379, 2023). "Expression of CXADR, BNIP3, or SPARCL1 was not downregulated by the ETV6/RUNX1 fusion in the absence of a viral infection (data not shown)." (PMID 41497616, 2025). "ITGAM, RUNX1, and PSTPIP2 formed one cluster with high expression in subjects with confirmed bacterial infections, whereas LY6E and IRF-9 formed another cluster with high expression, mainly in patients with confirmed viral infections." (PMID 36900096, 2023). "RUNX1 expression was upregulated by IFN-α2 treatment and virus infection." (PMID 36719379, 2023). "ITGAM, RUNX1, and PSTPIP2 formed one cluster with high expression in subjects with confirmed bacterial infections, whereas LY6E and IRF-9 formed another cluster with high expression in patients with confirmed viral infections." (PMID 36900096, 2023). "To address whether RUNX1 could indirectly modify phosphorylation of IRF3 and STAT1 upon viral infection, we infected the cells with PR8 at an MOI of 5, collected the cells at 3, 6, and 9 h.p.i." (PMID 35248104, 2022). "We did not detect phosphorylation of IRF3 and STAT1 in A549 cells of RUNX1 knockdown or overexpression without virus infection." (PMID 35248104, 2022). "To test whether RUNX1 could directly regulate IFN-β signaling, we analyzed the expression of IFNB1, MxA and ISG15 in the A549 cells without viral infection." (PMID 35248104, 2022).
asthma (6 papers, 2020 to 2025). "There are three runt-related transcriptional factor (RUNX) genes, namely RUNX1, RUNX2, and RUNX3, as well as maternal smoking, which have been reported to potentially support the onset of asthma in children by increasing the expression of RUNX1." (PMID 36675299, 2023). "Overall, we found that the sfFDR credible sets strongly overlapped with the informative traits (most with eosinophil count) except at the locus in RUNX1 where only 7.70% and 8.10% of the SNPs overlapped with the credible set for adult-onset asthma and childhood-onset asthma, respectively." (PMID 40846906, 2025). "We found RUNX1-p105/50 heterodimers and their co-localization in the nucleus in our asthma model." (PMID 37575259, 2023). "We speculate that NFκB1 positively regulated the effector phase of memory ILC2-induced asthma by heterodimerizing with RUNX1." (PMID 37575259, 2023). "Preferential expression of NFκB1 and RUNX1 in ILC2s implied a non-canonical heterodimer-mediated execution of the ILC2 effector function in our asthma model." (PMID 37575259, 2023).
Autoimmunity (6 papers, 2016 to 2025). The occurrence of an immune reaction against the organism's own cells or tissues. "An overexpression of Runx1 is associated with the pathogenesis of autoimmunity through Th17 cell induction." (PMID 37834058, 2023). "Moreover, some of these genes, such as USP19 and RUNX1, have been implicated in autoimmunity, therefore providing a rationale for examining how their splice isoforms might regulate immune responses." (PMID 38067106, 2023). "In naive T cells, RUNX1 plays a crucial role in maintaining cell quiescence as T cell specific deletion of RUNX1 leads to T cell hyperactivation and autoimmunity in mouse model." (PMID 40990016, 2025). "In summary, several pieces of evidence indicate a role for RUNX1 as a negative regulator of inflammation and autoimmunity." (PMID 37670378, 2023). "Importantly, the RUNX3 transcriptional activity is induced during the Epstein–Barr virus (EBV) infection of B cell immortality, leading to the repression of RUNX1, with both factors considered as interesting transcriptional regulators of autoimmunity." (PMID 30096841, 2018). "Moreover, in patients with autoimmunity, CD4+ T cells exhibited reduced RUNX1 and RASGRP1 expression, which was correlated to active inflammation." (PMID 37670378, 2023). "Thus, our study reveals a previously unrecognized synergism between ETV6/RUNX1 and BCL2 impacting on malignant disease and autoimmunity." (PMID 26919255, 2016).
childhood leukemia (6 papers, 2014 to 2023). An acute or chronic leukemia that occurs during childhood. "High hyperdiploid B-cell ALL and ETV6/RUNX1-positive pediatric ALL are among the most common subtypes of childhood leukemia." (PMID 37685286, 2023). "Genetic alterations affecting the process of megakaryopoiesis, such as MYH-9, ETV6, RUNX1, and ANKRD26 variants, have been reported to cause leukemic progression and are especially related to the genetic predisposition of childhood leukemia." (PMID 36534659, 2022). "In this study, we characterized the lncRNA expression signature associated with ETV6/RUNX1-positive BCP-ALL, one of the most prevalent genetic subtypes of childhood leukemia." (PMID 27650541, 2016).
chronic lymphoid leukemia (6 papers, 2008 to 2023). "The RUNX1 transcription factor gene is frequently mutated in sporadic myeloid and lymphoid leukemia through translocation, point mutation or amplification." (PMID 18671852, 2008). "RUNX1 was notably down regulated in chronic lymphoid leukemia samples." (PMID 22720055, 2012).